KDM5A (lysine demethylase 5A)
Diseases named in the same sentence as KDM5A in open-access papers (continued):
Sharing a sentence is not in itself a finding about the gene and the disease.
pancreatic cancer (8 papers, 2021 to 2026). "Intriguingly, we found that overexpression of KDM5A/C was associated with reduced sensitivity of pancreatic cancer cells to a variety of pancreatic cancer-targeting and chemotherapeutic drugs, such as axitinib and gemcitabine." (PMID 35493099, 2022). "However, the effect of KDM5A/B/C gene mutation on the prognosis of patients with pancreatic cancer needs to be further clarified in studies with a large sample size." (PMID 35493099, 2022). "Lysine demethylase 5A (KDM5A) promotes pancreatic cancer progression by redirecting mitochondrial pyruvate metabolism." (PMID 39062577, 2024). "Because KDM5A can lead to tumor cell chemotherapy resistance in a variety of cancers, we urgently need to further study the mechanism of drug resistance to develop new therapeutic targets for pancreatic cancer." (PMID 35493099, 2022). "Interestingly, the overexpression of KDM5A/C was also corelated with reduced sensitivity of pancreatic cancer cells to many kinds of pancreatic cancer-targeting or chemotherapeutic drugs, including axitinib and gemcitabine." (PMID 35493099, 2022). "Notably, epigenetic modifiers frequently showed more mutations in AYAs, including H3F3A, KDM5A and IDH1/2 in glioma, EP300 in liver cancer, SMARCA4 in ovarian cancer, and MEN1 in pancreatic cancer." (PMID 36433963, 2022). "Similarly, our study revealed that the expression of KDM5A can also reduce the sensitivity of pancreatic cancer cells to a variety of targeted and chemotherapeutic drugs (such as gemcitabine and paclitaxel)." (PMID 35493099, 2022). "In pancreatic cancer, MPC1 was also reported to be transcriptionally suppressed by Lysine demethylase 5 A (KDM5A)-mediated demethylation H3K4." (PMID 38615083, 2024). "The results showed that the expression levels of KDM5A and KDM5C were negatively correlated with sensitivity to many pancreatic cancer-targeting or chemotherapeutic drugs, including axitinib and gemcitabine." (PMID 35493099, 2022). "This discovery provides strong evidence for the study of KDM5A and KDM5C as targets for new pancreatic cancer-targeting and chemotherapeutic drugs." (PMID 35493099, 2022). "We employed multiple public databases to reveal that the expression of KDM5A, KDM5B, and KDM5C (all members of the KDM5 family) is significantly increased in pancreatic cancer." (PMID 35493099, 2022). "In addition, previous studies have demonstrated that KDM5A and KDM5C are overexpressed in gemcitabine-resistant pancreatic cancer cells and that their expression is regulated by CD44, a stem cell marker linked to chemoresistance." (PMID 39239542, 2024).
small cell lung carcinoma (8 papers, 2020 to 2025). Small cell lung cancer (SCLC) is a highly aggressive malignant neoplasm, accounting for 10-15% of lung cancer cases, characterized byrapid growth, and early metastasis. "For example, interfering with KDM5A expression or inhibiting its demethylase activity reduced tumor initiation and growth in RB-deficient mice, significantly expanding life span, and decreased cellular heterogeneity in a small cell lung cancer (SCLC) cell line." (PMID 35899196, 2022). "KDM5A also promotes tumorigenesis of small cell lung cancer suppressing target genes NOTCH1 and NOTCH2." (PMID 33596982, 2021). "KDM5A promotes small cell lung cancer tumorigenesis by repressing NOTCH signaling and sustaining ASLC1 expression." (PMID 33578894, 2021). "In addition, KDM5A can also promote the occurrence of small-cell lung cancer by inhibiting the target genes NOTCH1 and NOTCH2." (PMID 35493099, 2022). "KDM5A/RBP2 is a demethylase that suppresses NOTCH signaling, sustains neuroendocrine differentiation, and facilitates the development of small-cell lung cancer." (PMID 40282196, 2025). "The activation of Notch signaling suppresses tumorigenesis in small cell lung cancer (SCLC) by repressing the expression of neuroendocrine genes, suggesting an oncogenic function of KDM5A in SCLC." (PMID 35805040, 2022). "In gefitinib-tolerant human small-cell lung cancer PC9 cells, KDM5A specifically inhibits the proliferation drug-tolerant cells without affecting their parent cells via suppressing the expression of tissue factor pathway inhibitor 2 (TFPI2)." (PMID 33596982, 2021). "Ryuvidine, a KDM5A inhibitor identified by the AlphaScreen method, could prevent generation, and inhibit the growth of gefitinib-tolerant human small-cell lung cancer PC9 cells without affecting parental cells." (PMID 33596982, 2021).
ovarian carcinoma (7 papers, 2018 to 2025). A malignant neoplasm originating from the surface ovarian epithelium. "KDM5A is also an oncogenic driver, with overexpression of KDM5A observed in various cancers, including breast, lung, and ovarian cancer." (PMID 40545232, 2025). "In addition, KDM5A was shown to negatively correlate with CD8+ T cell infiltration in ovarian cancers, and the knockout of KDM5A reduced ovarian tumor burden in immunocompetent mice." (PMID 40940894, 2025). "In ovarian cancer, histone methylation regulates the TIME and immunotherapy efficacy through the actions of methyltransferases like SETDB1 and demethylases like KDM5A." (PMID 41029427, 2025). "For cervical cancer, therapies targeting MLL2 or m5C regulators like NSUN2 could restore immune recognition, while in ovarian cancer, inhibiting SETDB1 or KDM5A could enhance T-cell responses." (PMID 41029427, 2025).
glioma (6 papers, 2020 to 2023). A benign or malignant brain and spinal cord tumor that arises from glial cells (astrocytes, oligodendrocytes, ependymal cells). "Lower KDM5A levels were associated with poor survival in glioma patients." (PMID 37239035, 2023). "Another histone lysine demethyltransferase KDM5A shows a similar role but a different result in EMT in gliomas." (PMID 36338770, 2022). "RPTOR amplification was found to be significantly associated with young adult BRCA (FDR = 0.020), while amplifications of KDM5A, CCND2, KRAS, and ARRDC1 were each suggestively associated with young adult gliomas (FDR ≤ 0.148)." (PMID 34788626, 2021). "Lysine demethylase 5A (KDM5A), a member of histone demethylase and the most abundant KDM5 family member, is capable of removing tri- and dimethyl marks of Histone H3 lysine 4, which has been reported to inhibit the migration and invasion of glioma cells." (PMID 33499904, 2021).
Intellectual disability (6 papers, 2019 to 2026). "Whole-exome sequencing of individuals with intellectual disability has identified loss of function mutations in KDM5A, KDM5B and KDM5C." (PMID 31862793, 2019). "Changes to protein interactions could also contribute to the intellectual disability seen in individuals with genetic variants in KDM5A, KDM5B, or KDM5C." (PMID 36803422, 2023). "Loss-of-function mutations in the histone demethylases KDM5A, KDM5B or KDM5C are found in patients with intellectual disability and ASD." (PMID 41648108, 2026). "In contrast to the gain of function seen in cancer cells, loss of function variants in the autosomal paralogs KDM5A, KDM5B, and the X-linked KDM5C have been observed in individuals with intellectual disability." (PMID 36803422, 2023). "In contrast to intellectual disability, which is exclusively associated with loss-of-function mutations in KDM5 genes, malignancies have been associated with overexpression of KDM5A or KDM5B, either loss or gain of KDM5C, or loss of KDM5D." (PMID 31862793, 2019). "We found seven pathogenic KDM5A variants in patients with ASD, in conjunction with lack of speech, intellectual disability, and developmental delay." (PMID 33350388, 2020).
acute megakaryoblastic leukemia (5 papers, 2014 to 2025). Acute megakaryoblastic leukemia (AMKL) is a form of acute myeloid leukemia (AML) that occurs predominantly in childhood and particularly in children with Down syndrome (DS-AMKL). "These regions might reflect lineage-specific characteristics associated with acute megakaryocytic leukemia (M7) diagnosed in these NUP98::KDM5A-expressing samples." (PMID 40389480, 2025). "The JARID1A (KDM5A) H3K4 demethylase is fused to NUP98 in approximately 10% of pediatric acute megakaryoblastic leukemia resulting in the cytogenetically cryptic NUP98–JARID1A translocation." (PMID 29527516, 2018). "Despite generally low frequency of these genetic abnormalities in AMLs, the NUP98-JARID1A/KDM5A translocation was reported to be recurrent and detected in ~10% of the pediatric acute megakaryoblastic leukemia subtype." (PMID 29075615, 2017).
cervical cancer (4 papers, 2016 to 2024). A primary or metastatic malignant neoplasm involving the cervix. "Indeed, they discovered that KDM5A-induced E7 oncoprotein upregulation promoted the proliferation and invasiveness of cervical cancer cells in vitro and in vivo, which was associated with a poor prognosis in cervical cancer patients." (PMID 39684425, 2024). "As KDM5A is mainly localized in the nucleus, we examined the expression of KDM5A in the nucleus of cervical cancer cells treated with niraparib." (PMID 38869633, 2024). "Consistent with its effect on PD-L1, niraparib significantly increased the expression of KDM5A in cervical cancer cells." (PMID 38869633, 2024). "In summary, niraparib increased KDM5A expression in cervical cancer cells, which activated the PI3K-AKT-S6K1 signaling cascade and promoted PD-L1 accumulation." (PMID 38869633, 2024). "The structure and function of KDM5C is very similar to the highly tumourogenic KDM5A and KDM5B; it is overexpressed in cervical cancer and increased expression of this gene is associated with disease severity." (PMID 31766427, 2019). "To demonstrate the effect of niraparib on PD-L1 relied on KDM5A regulation of PTEN, we tested the efficacy of niraparib in KDM5A-knockdown cervical cancer cells." (PMID 38869633, 2024). "Neither the reduction in PTEN expression nor the expansion of PD-L1 abundance was observed in cervical cancer cells treated with the niraparib in the KDM5A knockdown cell lines." (PMID 38869633, 2024). "The expression of PD-L1 was inhibited in the KDM5A knockdown cervical cancer cells and the inhibition could not be relieved by the addition of niraparib, indicating the importance of KDM5A in the regulation of PD-L1 expression by niraparib." (PMID 38869633, 2024).
acute leukemia (3 papers, 2020 to 2022). A clonal (malignant) hematopoietic disorder with an acute onset, affecting the bone marrow and the peripheral blood. "NUP98 is frequently fused to a variety of genes in pediatric acute leukemias through translocations or inversions, for instance it can fuse to the PHD domain of KDM5A, forming NUP98-KDM5A." (PMID 34944554, 2021).
liver cancer (3 papers, 2016 to 2022). An epithelial or non-epithelial malignant neoplasm that arises from the liver. "Lysine demethylase 5A (KDM5A/RBP2/JARID1A) is a histone lysine demethylase that is overexpressed in several human cancers including lung, gastric, breast and liver cancers." (PMID 27224921, 2016).
acute promyelocytic leukemia (2 papers, 2022 to 2023). An aggressive form of acute myeloid leukemia (AML), characterized by arrest of leukocyte differentiation at the promyelocyte stage, due to a specific chromosomal translocation t(15;17) in myeloid cells. "A study of acute promyelocytic leukemia (APL) indicated that KDM5A contributes to the blockage of cell differentiation." (PMID 36799265, 2023). "In addition to NUP98–KDM5A fusion, KDM5A has been shown to be involved in the progression of acute promyelocytic leukemia (APL)." (PMID 35805040, 2022).
autism spectrum disorder (2 papers, 2020 to 2023). A spectrum of developmental disorders that includes autism, and Asperger syndrome. "Based on the association between genetic variants in KDM5A, KDM5B, and KDM5C and ID and autism spectrum disorder (ASD), KDM5-interactors could potentially be implicated in neurological disorders." (PMID 36803422, 2023).
congenital heart disease (2 papers, 2019 to 2023). "In another study, exome sequences revealed likely causal de novo variants in KMT2C and KDM5A, both histone methylases, that segregated with disease in a family with a history of congenital heart disease." (PMID 37504561, 2023). "Moreover, deleterious de novo mutations in KDM5A and KDM5B have been associated with congenital heart disease." (PMID 37504561, 2023).
diffuse intrinsic pontine glioma (2 papers, 2017 to 2019). A neuroglial tumor that arises from the middle portion of the brain stem. "In particular, KDM5A is involved in the acquisition of temozolomide (TMZ) resistance in adult GB cells and UDX/KDM6B regulates H3K27 methylation, which is involved in the pediatric diffuse intrinsic pontine glioma (DIPG)." (PMID 31238504, 2019). "Beside KDM1, KDM4A and KDM5A/5B are up-regulated in TMZ-resistant GB cells, KDM4B is up-regulated in response to irradiation and KDM6B was identified as a possible therapeutic target in the childhood Diffuse Intrinsic Pontine Glioma (DIPG)." (PMID 28432280, 2017).
kidney failure (2 papers, 2022 to 2024). An acute or chronic condition that is characterized by the inability of the kidneys to adequately filter the blood. "Interestingly, a recent study revealed that the inhibition of KDM5A can improve the protective effect of dexmedetomidine on renal failure." (PMID 36396833, 2022).
lung adenocarcinoma (2 papers, 2023). A carcinoma that arises from the lung and is characterized by the presence of malignant glandular epithelial cells. "HDAC inhibitors can also restore drug sensitivity in resistant lung adenocarcinoma PC9 cells, and removal of class I/II HDACs or KDM5A from HeLa and MCF-7 cells can enhance radiosensitivity." (PMID 37880235, 2023).
multiple myeloma (2 papers, 2022 to 2023). "We recently showed that KDM5A upregulates MYC target genes in multiple myeloma cells." (PMID 35805040, 2022). "Myeloma cell growth is halted by powerful and specific KDM5 inhibitors, verifying the oncogenic functions of KDM5A." (PMID 37218871, 2023). "KDM5A coexists with MYC and the components of the transcriptional machinery, including CDK7, CDK9, and RNAPII, across the genome of multiple myeloma cells." (PMID 35805040, 2022). "It preferentially binds KDM5A over other KDM5 isoforms, promotes H3K4me3 hypermethylation, and assists in MYC target downregulation and RNAPII phosphorylation; furthermore, it inhibits multiple myeloma cells." (PMID 37218871, 2023).
myeloid malignancies (2 papers, 2017 to 2021). "However, little is known about the role of full-length, enzymatically active, KDM5A in myeloid malignancies." (PMID 34944554, 2021). "Similar to KDM5A, evidence suggests a pro-leukemic role for KDM5B in myeloid malignancies." (PMID 34944554, 2021).
neuroendocrine neoplasm (2 papers, 2016 to 2024). Endocrine tumors, also referred to as neuroendocrine tumors (NETs), are defined by a common phenotype which is characterized by the expression of general markers (neuron specific enolase, chromogranin, synaptophysin) and hormone secretion products. "The findings of these two independent studies closely align with our finding that KDM5A plays a prominent role in neuroendocrine neoplasms." (PMID 38429350, 2024).
osteosarcoma (2 papers, 2021 to 2024). A usually aggressive malignant bone-forming mesenchymal neoplasm, predominantly affecting adolescents and young adults. "We also found that decreased osteosarcoma cell proliferation induced by KDM5A deficiency was associated with downregulation of cyclin D1 and upregulation of p27, P21, and apoptosis regulator Bax." (PMID 33436536, 2021). "In order to elucidate the mechanism underlying the antiproliferative effect of KDM5A in osteosarcoma, we carried out the transcriptome analysis on KDM5A-KO cells." (PMID 33436536, 2021). "Finally, this study provided a deeper understanding of the molecular mechanism of KDM5A underlying the osteosarcoma progression." (PMID 33436536, 2021). "Furthermore, the expression level of KDM5A was associated with osteosarcoma cell proliferation and tumor tumorigenesis." (PMID 33436536, 2021). "Accordingly, to evaluate the expression level, KDM5A was significantly upregulated in osteosarcoma tissues compared with the adjacent normal tissues." (PMID 33436536, 2021). "First, we found that KDM5A was upregulated in osteosarcoma tissues than the adjacent normal tissues." (PMID 33436536, 2021). "The present work illustrates that KDM5A is a potential oncogene in osteosarcoma via analysis of publicly available datasets, clinical subjects, and functional experiments." (PMID 33436536, 2021). "We observed the percentage of KDM5A-positive (KDM5A+), Ki67-positive (Ki67+), and KDM5A+/Ki67+ double-positive cells in the malignant osteosarcoma group was significantly higher than in the normal group, which was correlated with Enneking stages." (PMID 33436536, 2021). "In the present work, we examined the expression of KDM5A among human osteosarcoma tissues and its relationship with the clinical characteristic patients." (PMID 33436536, 2021). "Taken together, our research established a role of KDM5A in osteosarcoma tumorigenesis and progression." (PMID 33436536, 2021). "In order to evaluate the potential effect of KDM5A on osteosarcoma cell proliferation in vivo, the CRISPR/Cas9 system was used to knock out KDM5A in 143B cell lines." (PMID 33436536, 2021). "Thus, overexpression of KDM5A in osteosarcoma promotes cell proliferation by inducing cell-cycle-related genes and inhibiting apoptosis." (PMID 33436536, 2021). "Knockdown of KDM5A suppressed osteosarcoma cell proliferation and induced apoptosis." (PMID 33436536, 2021). "Furthermore, after knockout of KDM5A in osteosarcoma cells by CRISPR/Cas9 system, the tumor size and growth speed were inhibited in tumor-bearing nude mice." (PMID 33436536, 2021). "We also detected the increased expression of H3K4me3 in KDM5A-KO osteosarcoma cells." (PMID 33436536, 2021). "In the current study, KDM5A was highly expressed in osteosarcoma than adjacent normal tissue." (PMID 33436536, 2021). "Therefore, KDM5A as an oncogene in osteosarcoma through the function of histone demethylase needs further study." (PMID 33436536, 2021). "In conclusion, we have demonstrated that the expression of KDM5A was increased in osteosarcoma tissues, and reduced KDM5A level could decrease osteosarcoma cell growth in vitro and prevent osteosarcoma tumorigenesis in vivo." (PMID 33436536, 2021). "Moreover, the potential role of KDM5A on the proliferation of osteosarcoma was investigated." (PMID 33436536, 2021). "Therefore, KDM5A may also promote the metastasis of osteosarcoma." (PMID 33436536, 2021). "However, the expression of KDM5A and its clinical significance in osteosarcoma remains unclear." (PMID 33436536, 2021). "RNA-Seq of KDM5A-KO cells indicated that interferon, epithelial–mesenchymal transition (EMT), IL6/JAK/STAT3, and TNF-α/NF-κB pathway were likely involved in the regulation of osteosarcoma cell viability." (PMID 33436536, 2021). "However, the function of KDM5A in the carcinogenesis of osteosarcoma is not clear." (PMID 33436536, 2021).
renal failure (2 papers, 2022 to 2025). "However, in LPS-induced AKI mice, DEX can effectively mitigate sepsis-induced renal failure by inhibiting the NF-κB-mediated demethylase KDM5A." (PMID 40989844, 2025).
Sepsis (2 papers, 2024 to 2025). Sepsis is defined as life-threatening organ dysfunction caused by a dysregulated host response to infection. "DEX could attenuate AKI through KDM5A inhibition in sepsis, transcription and protein levels of genes such as TLR4, MYD88, MTA1, PTGS2, CASP3 associated with NF-κB signaling pathway were all compromising after treated with DEX." (PMID 40989844, 2025).